APOE (apolipoprotein E)
Diseases named in the same sentence as APOE in open-access papers (continued):
Sharing a sentence is not in itself a finding about the gene and the disease.
atherosclerosis (continued). "More importantly, silencing of CHI3L1 diminished atherosclerotic burden and increased plaque stability in ApoE−/− mice, and it might provide a new therapeutic approach to the treatment of atherosclerosis." (PMID 24729664, 2014). "In the current study, we evaluated whether CGA protects against atherosclerosis development in ApoE−/− mice fed a cholesterol-rich diet." (PMID 25187964, 2014). "ApoE−/− mice spontaneously developed atherosclerosis after fed with HCD for 14 weeks (Fig. 6A3)." (PMID 24465540, 2014). "Genetic inactivation of Cxcr3 or its ligand Cxcl10, that were both detected in mouse lesions in the ApoE−/− strain, resulted in decreased atherosclerosis burden that was accompanied by a decrease in inflammatory CD4+ T cell content, an elevated number of Tregs, and increased expression of IL-10." (PMID 24741577, 2014). "In present studies, we investigated the effect of OEA on the course of atherosclerosis development in clinically relevant animal models, i.e., high-caloric diet (HCD)-induced atherosclerosis in arterial denudated rats and HCD-induced atherosclerosis in ApoE null-mice (ApoE−/−)." (PMID 24465540, 2014). "Importantly, atherosclerosis-prone apolipoprotein E-null (ApoE−/−) mice had a 3-fold up-regulation in plasma and smooth muscle cell PAI-1 mRNA in advanced atherosclerotic lesions compared to wild-type controls suggesting a role in disease progression." (PMID 26110015, 2014). "Therefore, the present study is to investigate the effects of salusin-α and salusin-β on the vascular inflammation of atherosclerosis through continuous infusion of salusins into ApoE-/- mice." (PMID 24621517, 2014). "This was proved in the advanced atherosclerosis model in ApoE−/− mice, finding strong positivity not only in endothelial cells but also in the subendothelial space, correlating with the progression of the disease as well as the infiltration level of macrophages and platelets in the lesion site." (PMID 25328689, 2014). "However, the ApoE gene is closely associated with porcine plasma ApoE protein, LDL and cholesterol concentration, atherosclerosis, and Alzheimer's disease." (PMID 25006576, 2014). "Atherosclerosis-prone ApoE−/− mice were orally infected with P. gingivalis strains 381, PG1587381, and PG1773381 and chronic inflammation at local (oral bone loss) and systemic (atherosclerosis) sites was evaluated." (PMID 25010102, 2014). "Moreover, and most relevantly, genetic ablation of Nox1 was shown to greatly reduce the extent of diet-induced atherosclerosis in ApoE-null mice." (PMID 24587793, 2014). "There is no doubt that CXCL4 is important for atherosclerosis since the deletion of the PF4 gene that encodes CXCL4 reduces atherosclerotic lesions in apoE deficient mice." (PMID 24847266, 2014). "Over-expression of HMOX1 inhibits atherosclerosis in ApoE-/- mice." (PMID 25635207, 2014). "DMHCA, however, reduced atherosclerosis in apolipoprotein E-deficient mice without inducing hypertriglyceridemia and liver steatosis." (PMID 25136342, 2014). "Meanwhile, the expressions of IL-6, TNF-α, MCP-1 and VCAM-1 were up-regulated in apoE-/- mice treated with salusin-β, indicating that salusin-β could aggravate the progression of atherosclerosis via up-regulation of inflammatory molecules." (PMID 24621517, 2014). "Indeed, it has been demonstrated that genetic or pharmacologic ablation of NO synthase (NOS) accelerates atherosclerosis in the ApoE-null mouse." (PMID 24587793, 2014).
atherosclerosis (continued). "Since elevated levels of serum cholesterol are probably unique in being sufficient to drive the development of atherosclerosis in humans, we aimed to identify whether miR-144-3p agomir affects the lipid parameters in apoE−/− mice administered HFD." (PMID 24733347, 2014). "In summary, the present study found that exogenous salusin-β, but not salusin-α, could directly promote vascular inflammation in apoE-/- mice via the I-κBα/NF-κB pathway, resulting in the aggravation of atherosclerosis." (PMID 24621517, 2014). "However, the fact that the genetic ablation of miR-33 protects against the progression of atherosclerosis in apoE−/− mice suggests that long-term anti-miR-33 therapy should be beneficial for treating atherosclerotic vascular disease." (PMID 25038053, 2014). "We observed increased expression of several of these genes in aortic tissue from untreated ApoE-/- mice fed a normal chow diet, which represents the natural progression of atherosclerosis; and, in ApoE-/- WD mice, we observed an even greater increase in expression of some of these genes." (PMID 25540039, 2014). "Based on increased HDL and decreased VLDL + LDL, DKO mice of either gender might be expected to be protected from atherosclerosis compared with ApoE KO mice." (PMID 25389425, 2014). "In addition, XOR inhibitors such as tungsten and allopurinol inhibited the progression of atherosclerosis in ApoE−/− mice." (PMID 24686534, 2014). "Constitutive ApoE−/− mice generated through partial replacement of exon 3 and part of intron 3 of the ApoE gene by a neomycin cassette are a model for experimental atherosclerosis and develop a renal phenotype similar to that observed in patients with type III hyperlipoproteinemia and LPG." (PMID 25352833, 2014). "Apolipoprotein E knockout (ApoE−/−) mice exhibit chronic hypercholesterolaemia and go on to develop early and spontaneous atherosclerotic lesions and as such, are a widely used model of atherosclerosis." (PMID 24630173, 2014). "Data suggest that cola beverages drinking during early life stages may accelerate worsening of atherosclerotic damagelater in life in a genetically favorable scenario, namely as found in the atherosclerosis-prone ApoE−/− mice." (PMID 24670925, 2014). "The apoE-null mice showed some characters of atherosclerosis and insulin resistance." (PMID 24526524, 2014). "In addition, after 5-month exposures, nano-NH NPs exacerbated the progression of athero sclerosis in ApoE−/− mice." (PMID 25268624, 2014). "In addition, the disruption of Scarb1 gene in atherosclerotic mice (APOE -/-) accelerates the onset of atherosclerosis." (PMID 25379707, 2014). "ApoE−/− mouse was an animal model widely used to study the development of atherosclerosis." (PMID 25268624, 2014). "Moreover, the importance of T cells in atherogenesis has been highlighted by animal studies showing that transfer of CD4+ T cells aggravates, whilst depletion of CD4+ T cells attenuates atherosclerosis in apoE-/- mice." (PMID 25253303, 2014). "In the present study, we assessed the impact of CKD on the ADMA/DDAH axis in atherosclerosis by studying atherosclerotic lesion formation in subtotally nephrectomized (SNX) ApoE-deficient mice with or without overexpression of DDAH1." (PMID 24690995, 2014). "Aged ApoE−/− mice with advanced atherosclerosis have lower levels of CXCL12 in serum and bone marrow than their age matched controls, indicating that CXCR4-CXCL12 axis may counter plaque development." (PMID 24741577, 2014).
atherosclerosis (continued). "The ApoE KO mouse model is the classical model of atherosclerosis." (PMID 25017431, 2014). "Overexpression of the ADMA degrading enzyme, DDAH1, did not ameliorate atherosclerosis in ApoE-deficient SNX mice." (PMID 24690995, 2014). "Atherosclerosis prone 22 week old ApoE−/− mice were treated as outlined in PROTOCOL I." (PMID 23755169, 2014). "Mice homozygous for apolipoprotein E (apo E−/−) exhibit a marked increase in the plasma level of total cholesterol, accompanied by the progression of atheromatous plaque with age, which resembles human atherosclerosis." (PMID 25153991, 2014). "Due to the previous fact, the objective of this work was to study through immunochemistry the participation of endothelium, monocyte/macrophage, and platelets in a metabolic syndrome (MS) model obtained in CF-1 mice and in an advanced atherosclerosis model obtained in ApoE−/− mice." (PMID 25328689, 2014). "For example, a recent study reported that treatment with oleanolic acid had beneficial effects on the development of atherosclerosis in apolipoprotein E knockout mice, which may be due to its antioxidant properties." (PMID 24393202, 2014). "Low-dose FK506 (∼0.2 ng/mL) inhibited collar-induced atherosclerosis progression and promoted plaque stability in ApoE−/− mice, whereas higher doses similar to those given to transplant patients engaged instead NF-κB in macrophages and consequently increased production of cytokines." (PMID 23755169, 2014). "Our study shows that in vivo CSE/H2S overexpression protects ApoE-KO mice from atherosclerosis." (PMID 25397776, 2014). "Although atherosclerosis is not a distinguishing feature described in ApoE-deficient humans, ApoE-deficiency alone proved to be sufficient for aortic atherosclerotic plaques to develop in mice." (PMID 24062791, 2013). "Using ApoE deficient mice, we examined whether KB3495, a TH mimetic compound, reduces atherosclerosis and if there is a synergistic effect with atorvastatin." (PMID 24324578, 2013). "Thus, the decreased progression of atherosclerosis in AdipoR2-/-ApoE-/- mice was likely due to other mechanisms than decreased inflammation." (PMID 24324556, 2013). "Since NEFA induces ER stress and inflammation, the decrease in NEFA may explain the attenuation of atherosclerosis in the Herp−/−;apoE−/− mice." (PMID 24204574, 2013). "With the development of a small molecular weight elastin specific gadolinium based MR contrast agent (ESMA), MRI of remodeling at all stages of atherosclerosis has become feasible and has been recently demonstrated in an apoE−/− mouse model of accelerated atherosclerosis." (PMID 24232739, 2013). "In addition, the effect of celastrol on atherosclerosis in vivo was assessed in apolipoprotein E knockout (apoE−/−) mouse fed a high-fat/high-cholesterol diet (HFC)." (PMID 23799016, 2013).
atherosclerosis (continued). "In agreement with inhibition of the aortic recruitment of pro-inflammatory T cells by captopril, ACE inhibitor treatment with captopril prevented the atherosclerosis-related increase in the aortic content of the T cell-specific Cd8b protein of ApoE−/− mice as determined by immunoblotting." (PMID 23801967, 2013). "Mice that are double knockout for Apolipoprotein E (APOE) and FABP4 are protected from atherosclerosis compared to the APOE knockout alone; bone marrow transplantation studies have shown that this atheroprotective effect is mainly due to the absence of FABP4 in macrophages." (PMID 23122912, 2013). "Finally, fibrate PPAR-α activators have been reported to potently reduce atherosclerosis both in apoE−/− mice and in human ApoAI transgenic apoE−/− mice." (PMID 23781121, 2013). "The present study examined the effect of 2-AP on atherosclerosis in apoE−/− mice." (PMID 23984090, 2013). "Similarly, apoE knockout (apoE−/−) mice manifest an elevated plasma cholesterol and develop atherosclerosis in a manner that resembles the human disease." (PMID 23984090, 2013). "Germ-line deletion of p110γ in ApoE−/− mice attenuates murine atherosclerosis." (PMID 23991137, 2013). "In apoE-knockout mice, an animal model with dyslipidemia, high oxidative stress, and pronounced atherosclerosis after uninephrectomy, the animals developed reduced plaque growth and calcification with vitamin D analog treatment (paricalcitol) compared with control groups." (PMID 23800102, 2013). "However, peritoneal macrophages from Adrp knockout mice accumulate fewer LDs upon cholesterol loading, and in atherosclerosis-prone apoE knockout mice, ADRP depletion decreases the number of LDs in foam cells, yet protects mice from atherosclerosis." (PMID 23740690, 2013). "To determine whether anti-BAFFR antibody ameliorates progression of atherosclerosis, we first fed ApoE−/− mice a HFD for 6 weeks, and then instigated anti-BAFFR antibody treatment for a further 6 week-HFD." (PMID 23560095, 2013). "Given that B2 lymphocytes are dependent on the interaction of BAFF (B cell activation factor of the TNF family) with BAFF-receptor (BAFFR) for their survival and maturation, we crossed BAFFR-deficient mice to ApoE−/− mice and examined how BAFFR deficiency affected development of atherosclerosis." (PMID 23560095, 2013). "The deficiency of Herp significantly suppressed the development of atherosclerosis in apoE−/− mice." (PMID 24204574, 2013). "Previous studies examining the progression of atherosclerosis in ApoE−/− mice found that CSE activity and endogenous H2S production were inhibited in this model, results that concur with other data showing an inverse relationship between plasma H2S levels and cardiovascular disease." (PMID 23864951, 2013). "Importance of diet and role of TNF-α in atherosclerosis progression was further substantiated by a study in which the authors showed that ApoE−/−/TNF-α−/− double knockout mice had a 50% reduction in lesion size relative to ApoE−/− single knockouts when put on ‘Western-style’ high-fat diet." (PMID 23437105, 2013). "Plasma SM levels in atherogenic apoE KO mice are fourfold higher than in wild type mice and this may contribute to the increased atherosclerosis." (PMID 23761785, 2013). "Mice deficient in both AdipoR2 and ApoE (AdipoR2-/-ApoE-/-) and littermate control mice lacking only ApoE (AdipoR2+/+ApoE-/-) were generated to study the effect of AdipoR2 deficiency on the progression of atherosclerosis." (PMID 24324556, 2013). "The present report studied the effect of 2-AP on atherosclerosis in apoE−/− mice." (PMID 23984090, 2013). "The ApoE-/- mouse was used as a model of atherosclerosis and metabolic disorder because of the potential implications of the resulting information on some individuals with personal or familiar history of atherosclerosis or metabolic disorders." (PMID 23547749, 2013). "Oxidation of ApoE plays a crucial role in the genesis of atherosclerosis." (PMID 23451244, 2013).
atherosclerosis (continued). "Our previous study has shown that betaine has an anti-atherosclerosis effect in the ApoE−/− mice." (PMID 23497035, 2013). "Transplantation of bone marrow (BM) stem cells from donor mice lacking SR-BI into recipient LDL receptor KO, apoE KO or wild type mice increases their susceptibility to atherosclerosis." (PMID 23967310, 2013). "The specific aims of this study were to examine the role of both endogenously produced H2S and chronic exogenous H2S treatment in vivo on a lesion development, vascular superoxide generation, and endothelial function in the fat-fed ApoE−/− mouse model of atherosclerosis." (PMID 23864951, 2013). "GO analysis of probe sets with significantly higher expression after treatment compared to untreated ApoE−/− aortas and immunohistology analysis revealed that vitamin E treatment and ACE inhibition prevented the atherosclerosis-related down-regulation of aortic intima genes of ApoE−/− mice." (PMID 23801967, 2013). "Notably, the atherosclerosis-prone aorta of ApoE−/− mice was characterized by a significant down-regulation of multiple nerve-specific genes." (PMID 23801967, 2013). "Furthermore, knocking out apoA-I resulted in an accelerated atherosclerosis development in several animal models (i.e. the human apoB-transgenic female mice; the LDL receptor-deficient; the LDL receptor/apoE-deficient mice)." (PMID 23552612, 2013). "We generated mice deficient in both AdipoR2 and ApoE (AdipoR2-/-ApoE-/-) and littermate control mice lacking only ApoE (AdipoR2+/+ApoE-/-) in order to study the impact of AdipoR2 deficiency on the atherosclerosis process." (PMID 24324556, 2013). "Therefore, the decreased atherosclerosis in AdipoR2-/-ApoE-/- mice compared with AdipoR2+/+ApoE-/- controls must be explained by other mechanisms than reduced plasma cholesterol levels." (PMID 24324556, 2013). "Recent study shows that both eNOS and nNOS significantly inhibit atherosclerosis in ApoE KO mice." (PMID 24062791, 2013). "The aim of the present study was to test the hypothesis that chronic sildenafil treatment could revert or reduce the endothelial dysfunction and the progression of atherosclerosis observed in large vessels of apoE−/− mice." (PMID 23289368, 2013). "Providing further support for a causal relationship between activated T cells and the induction of atherosclerosis we could also show a clear reduction in apoE secretion in PBMC containing stimulated T cells." (PMID 24244577, 2013). "SR-BI/apoE double KO mice rapidly (within 6 weeks of age) develop occlusive coronary artery (CA) atherosclerosis and exhibit extensive myocardial fibrosis, ECG abnormalities, cardiac enlargement, reduced heart function (ejection fraction, contractility and relaxation) and early death." (PMID 23967310, 2013). "In the current work we had two major objectives to study the effect of Dunaliella on the progression of established atherosclerosis in the apoE−/− mouse model and to investigate whether the effect of Dunaliella is influenced by the dietary fat content." (PMID 24175283, 2013). "In two distinct experimental setups (spontaneous and collar-induced atherosclerosis), we show that genetically-imposed 50% reduction in prothrombin (FII−/+) in atherosclerosis-prone ApoE−/− mice remarkably diminishes lesion formation and promotes plaque stability." (PMID 23409043, 2013). "The ApoE−/− mouse strain is a well-established model for atherosclerosis." (PMID 23691261, 2013). "Atherosclerosis in ApoE-/- mice can be affected by several factors." (PMID 23547749, 2013). "Decreased HSP27 expression may be an important factor in the development of atherosclerosis; hence to address this question we performed acute studies of atherosclerosis-prone apoE−/− mice that over-express HSP27 (i.e., apoE−/−HSP27o/e)." (PMID 23409070, 2013). "Pathologically, ApoE plays similar roles in genesis of atherosclerosis in both mouse and humans." (PMID 23451244, 2013).